ZNF423 (zinc finger protein 423)
Diseases named in the same sentence as ZNF423 in open-access papers (continued):
Sharing a sentence is not in itself a finding about the gene and the disease.
Lipedema (4 papers, 2022 to 2026). Disorder of adipose tissue characterized by symmetric and bilateral enlargement of the lower extremities due to abnormal deposition of subcutaneous fat often in obese women. "Additional insights into estrogen-related dysregulation were provided by the finding of upregulated aromatase and ZNF423 expression in perivascular adipose populations of lipedema patients, suggesting enhanced preadipocyte commitment." (PMID 41575573, 2026). "Surprisingly, lipedema-derived abdominal EC also showed a significantly increased ZNF423 gene expression (p = 0.019)." (PMID 35625899, 2022). "We detected a significantly increased ZNF423 expression in lipedema thigh compared to healthy thigh-derived SVF, isolated PC, and an even stronger increase in isolated CD31+ EC." (PMID 35625899, 2022). "A significant upregulation of the transcription factor ZNF423 (Zfp423) in lipedema SVF cells compared to controls was reported recently." (PMID 36675759, 2022). "ZNF423 expression in preadipocytes is related to the activation of PPARG and directly to the maturation of adipocytes; thus, upregulation of ZNF423 is a potential mechanism by which estrogen promotes hyperproliferation in lipedema." (PMID 36551837, 2022). "Since ZNF423 is critically involved in early adipocyte commitment, a potential dysregulation of lipedema adipose tissue formation at an early stage of mesenchymal stem cell differentiation is possible." (PMID 36675759, 2022). "Of note, EC sorted from the supposedly unaffected abdominal subcutaneous AT of lipedema patients likewise showed increased ZNF423 expression." (PMID 35625899, 2022). "The upregulation of ZNF423 could potentially explain the lower thermogenic rate of AT in lipedema fat by maintaining the white phenotype of AT and suppressing the brown–beige characteristics." (PMID 36551837, 2022). "The higher expression of ZNF423 may also contribute to the hyperproliferative phenotype of AT in lipedema." (PMID 36551837, 2022). "However, the expression of PPARγ, a down-stream target of ZNF423, only slightly increased in lipedema thigh PC, compared to healthy controls." (PMID 35625899, 2022). "Moreover, we found a potential link of estrogen to preadipocyte commitment and subsequent fat mass expansion via the increased expression of aromatase in adipose tissue and ZNF423 in perivascular subpopulations in lipedema." (PMID 35625899, 2022). "In summary, our gene expression analysis revealed a possible involvement of local estrogen metabolism, as well as a dysregulation of ZNF423 in SVF, EC and PC, and hence a possible role of endothelium-related cells (EC and PC) in lipedema." (PMID 35625899, 2022).
medulloblastoma (3 papers, 2013 to 2016). A malignant, invasive embryonal neoplasm arising from the cerebellum. "ZNF423-depleted DAOY medulloblastoma cells are reproducibly deficient in translocation into the cilium of both Smoothened and IFT88, which are required for normal signal processing and specifically for expansion of GCPs." (PMID 27727273, 2016). "DAOY is a human medulloblastoma-derived cell line that expresses markers consistent with a GCP lineage and ZNF423, the human homologue of Zfp423." (PMID 27727273, 2016).
nasopharyngeal carcinoma (3 papers, 2015 to 2025). A carcinoma arising from the nasopharyngeal epithelium. "The recent report of a recurrent gene fusion of UBR5 on 8q22.3 and ZNF423 on 16q12.1 (UBR5-ZNF423) in 8 % of EBV-associated primary nasopharyngeal carcinomas suggests a driver function of this gene fusion in a subset of nasopharyngeal cancers." (PMID 26684754, 2015). "The fusion of locus 8q22 and zinc finger protein 423 (ZNF423) on 16q12 was also identified in head and neck cancer primary tumors where downregulation of this fusion inhibits cell proliferation in nasopharyngeal carcinoma." (PMID 32867711, 2020). "Moreover, recurrent UBR5::ZNF423 and FGFR3::TACC3 fusions have been detected in 8.3% and 2.5% of nasopharyngeal carcinomas, another rare virally induced head and neck carcinoma type." (PMID 39387893, 2025).
nephronophthisis (3 papers, 2016 to 2020). Progressive tubulointerstitial injury, inherited in an autosomal recessive pattern, caused by mutations in genes involved in ciliary function, which may result in an end stage renal failure. "Largely identified in nephronophthisis, mutations within DDR genes such as ZNF423, CEP164, NME3, and AATF are sufficient to cause disease via ciliary dysfunction." (PMID 32351541, 2020).
glioma (2 papers, 2016). A benign or malignant brain and spinal cord tumor that arises from glial cells (astrocytes, oligodendrocytes, ependymal cells). "We revealed a novel three-transcription-factor signature including AHR, NFIL3 and ZNF423 for glioma molecular subtypes." (PMID 27586240, 2016). "The expression values of AHR, NFIL3 and ZNF423 across glioma subtypes are significantly different." (PMID 27586240, 2016). "We observed that also in gliomas, ZNF423 downregulation correlated with higher grade." (PMID 26923714, 2016). "Therefore, we checked if these three transcription factors (AHR, NFIL3 and ZNF423) could be a glioma prognosis-related signature by measuring its clinical relevance with NMF clustering method and survival analysis." (PMID 27586240, 2016). "Thus, to generalize our findings and test whether ZNF423 behaved similarly in gliomas, we performed a meta-analysis of a large cohort of expression data from 343 samples of human gliomas deposited at the NCI REpository for Molecular BRAin Neoplasia DaTa46." (PMID 26923714, 2016). "We investigated the relevance of the three-TF signature to regulation mechanisms of glioma carcinogenesis and suggested AHR, NFIL3 and ZNF423 as promising biomarkers for not only glioma molecular subtype diagnosis but also clinical treatment." (PMID 27586240, 2016). "In this study, we analysed 6 public transcriptome glioma data sets and identified three glioma prognosis-related transcription factors, AHR, NFIL3 and ZNF423." (PMID 27586240, 2016).
systemic lupus erythematosus (2 papers, 2010 to 2019). An autoimmune multi-organ disease typically associated with vasculopathy and autoantibody production. "Furthermore, elevated gene-expression of ZNF423 has been shown to occur in patients with systemic lupus erythematosus, pointing to an impaired function of B cells in human mesenchymal stem cells." (PMID 31283791, 2019).
acute lymphoblastic leukemia (1 paper, 2018). Leukemia with an acute onset, characterized by the presence of lymphoblasts in the bone marrow and the peripheral blood. "In ETV6-Runx1 negative B precursor acute lymphoblastic leukemia (ALL), aberrant expression of ZNF423 induced by epigenetic deregulation inhibits EBF target genes and leads to B cell maturation arrest associated with poor outcome." (PMID 29867779, 2018).
Age-related cataract (1 paper, 2021). A type of cataract (opacification of the lens) that forms during the course of aging. "Some of these genes associated with age-related cataracts include FRMD4B, NAALADL2, LOC105377670, LINC00968, LOC101929415, CTNNA3, LOC107984170, PRCP, and ZNF423, whereas others with a reduced risk include CFAP74, ACSL1, LOC101927668, LOC105369844." (PMID 34299682, 2021).
Alzheimer disease (1 paper, 2019). A progressive, neurodegenerative disease characterized by loss of function and death of nerve cells in several areas of the brain leading to loss of cognitive function such as memory and language. "The ZNF423 gene resides in an Alzheimer’s disease-specific protein network and is likely involved with centrosomes and DNA damage repair." (PMID 31283791, 2019).
brain aneurysm (1 paper, 2023). A congenital or acquired aneurysm within the cranium. "Brain aneurysm was observed in eight patients (16%), and the causative genes were PKD1 (missense (n = 2), nonsense (n = 1)), PKD2 (missense (n = 1), splice-site (n = 1)), ZNF423 (missense), GLIS2 (missense) or PKHD1 (missense) or WDR19 (splice-site), and CEP164 (missense)." (PMID 36833371, 2023).
cholangiocarcinoma (1 paper, 2019). A carcinoma that arises from the intrahepatic biliary tree (intrahepatic cholangiocarcinoma) or from the junction, or adjacent to the junction, of the right and left hepatic ducts (hilar cholangiocarcinoma). "Zinc finger protein 423 (ZNF423) is a transcriptional factor involved in the development and progression of cancers but has not yet been examined in cholangiocarcinoma (CCA), an oxidative stress-driven cancer of biliary epithelium." (PMID 31284679, 2019).
lymphedema (1 paper, 2021). Excess fluid collection in tissues, causing swelling. "Nevertheless, preadipocytes derived from lymphedema subjects exhibited differential expression of GDF15, the marker of mitochondrial stress, and of KLF4, KLF6, INHBA and ZNF423, i.e. genes implicated in adipogenesis, when compared with cells from healthy women." (PMID 33854130, 2021).
teratocarcinoma (1 paper, 2013). A germ cell tumor characterized by the presence of an embryonal carcinoma component and a teratoma component. "As much of the biology of ZNF423/Zfp423 has been studied in mice, we also examined a commonly used mouse teratocarcinoma cell line with neurogenic potential, P19, which was previously reported to express Zfp423 and PARP." (PMID 23762491, 2013).
thyroid tumor (1 paper, 2023). A benign or malignant neoplasm affecting the thyroid gland. "Our study provides evidence that OCLN, ZNF423, LYG1, and AQP5 mRNA markers can serve as reliable molecular markers for identifying NIFTP among other thyroid tumors." (PMID 37658903, 2023). "Our results suggest that OCLN, ZNF423, LYG1, and AQP5 mRNA markers might serve as reliable molecular markers for identifying NIFTP among other thyroid tumors, ultimately aiding in accurate diagnosis and management of NIFTP patients." (PMID 37658903, 2023).
tumor (9 papers, 2016 to 2025). "ZNF423 has been implicated in the regulation of tumor growth, cell proliferation, and apoptosis." (PMID 37658903, 2023). "An inverse relationship between EBF1 expression and ZNF423 (Zinc Finger Protein 423) levels in tumor tissues leads to unfavourable prognostic outcomes." (PMID 39236081, 2024). "The results showed that ZNF423 was overexpressed in CCA cells compared to normal bile duct cells adjacent of the tumor." (PMID 31284679, 2019). "On the other hand, ZNF423 acts as a tumor suppressor in both NB and BC." (PMID 31284679, 2019). "Additionally, the loss of the neurofibromin 1 (NF1) tumor suppressor induces activation of RAS-MEK signaling, which in turn repressed ZNF423 mRNA and protein expression." (PMID 29867779, 2018).
cancer (6 papers, 2013 to 2023). A tumor composed of atypical neoplastic, often pleomorphic cells that invade other tissues. "Moreover, ESR1 and ZNF423 have a role in cancer cell proliferation and were significantly associated with platinum-sensitive tumors." (PMID 31554806, 2019). "ZNF423 plays different roles in various cancer cell types depending on its downstream interactions, tissues specific contents and the multiple functional domains (30 domains)." (PMID 31284679, 2019). "Therefore, the roles of ZNF423 in other cancers e.g., EBFs-, retinoic acid-, and estrogen-related cancer developments should be investigated to gain further basic knowledge and improve treatment outcome for these diseases." (PMID 31284679, 2019). "Notably, CCA patients who had high ZNF423 and 8-oxodG levels in the cancer tissues have significantly shorter survival." (PMID 31284679, 2019). "ZNF423, which was not previously associated with BC is a multifunctional transcription factor known to have a role in development, neurogenesis, and adipogenesis and is implicated in other types of cancer." (PMID 29867779, 2018). "ZNF423 and its related proteins might be novel targets for CCA chemotherapy towards a further increase of survival rates and hereby improve the cancer patients’ quality of life." (PMID 31284679, 2019).
hematological disease (1 paper, 2021). "Genes highlighted here in, such as PRDM16, PER3, NOM1 BAHCC1, ZNF423, SETD7, RPTOR, and others have been implicated in hematological disease development, progression or clinical outcome." (PMID 34200630, 2021).
metabolic disease (1 paper, 2017). A congenital disorder (due to inherited enzyme abnormality) or acquired (due to failure of a metabolically important organ) disorder resulting from an abnormal metabolic process. "Because of the interaction of miR-23a and ZNF423, miR-23a may also potentially regulate energy metabolism and involve in the etiology metabolic diseases." (PMID 28255176, 2017).
neurodevelopmental disorder (1 paper, 2020). A behavioral and cognitive disorder with onset during the developmental period that involves impaired or aberrant development of intellectual, motor, or social functions. "ZNF423 has been implicated in rare neurodevelopmental disorders, consistent with midline brain defects in Zfp423-mutant mice, but pathogenic potential of most patient variants remains uncertain." (PMID 32925911, 2020). "For example, ZNF423 mutations have been reported as pathogenic in JSRD patients and other neurodevelopmental disorders, but most patient variants have uncertain significance and even those asserted pathogenic in public databases rely on very limited data." (PMID 32925911, 2020).
ZNF423 also shares sentences with these, for which no sentence is quoted: head and neck carcinoma (2 papers); ovarian cancer (2); amyotrophic lateral sclerosis (1); Ataxia (1); B-cell lymphomas (1); bipolar disorder (1); cataract (1); Dandy-Walker syndrome (1); depression (1); diabetes (1); glioblastoma (1); glucose metabolism disorders (1); Huntington disease (1); Hyperglycemia (1); Insulin resistance (1); liposarcoma (1); lung carcinoma (1); malignant peripheral nerve sheath tumor (1); orofacial cleft (1); osteogenesis imperfecta (1); Salmonella Infections (1); Wilms tumor (1).